TLR4 (toll like receptor 4)
Diseases named in the same sentence as TLR4 in open-access papers (continued):
Sharing a sentence is not in itself a finding about the gene and the disease.
bacterial infection (continued). "Following a mixed bacterial infection, the experimental groups showed significantly higher levels of NFκB, TLR4, IL-6, TNF-α, and IL-1β compared to the control group (p < 0.05)." (PMID 40136393, 2025). "LPS, a Toll-like receptor 4 (TLR4) agonist that mimics bacterial infection, triggers signal transduction and activates transcription factors such as nuclear factor kappa B (NF-κB)." (PMID 40192828, 2025). "TLR4 and TLR2 are identified as key receptors participating in pathogenic inflammatory responses under bacterial infection." (PMID 40963927, 2025). "TLR2 and TLR4 are the most critical PRRs during bacterial infection and function to promote inflammatory responses upon invasion of bacteria." (PMID 38182816, 2024). "TLR-2 and TLR-4 are the two major TLRs that recognize PAMPs during bacterial infections and have been extensively studied and evaluated in A. baumannii infection." (PMID 39149030, 2024). "This inhibition of acidification in the signaling endosome blocked signal transduction from interferon-alpha/beta receptor (IFNAR) and TLR4, two receptors critical to generating immune responses to bacterial infections." (PMID 39776898, 2024). "TLR4 is a pattern recognition receptor that regulates inflammation during viral and bacterial infections." (PMID 38807115, 2024). "It is evident that TLR4 and the signaling pathways that it interacts with downstream play a critical role in triggering the release of inflammatory cytokines during bacterial infection." (PMID 39394128, 2024). "Dengue non-structural protein 1 (NS1) directly induces glycocalix shedding of lung endothelium through the upregulation of cathepsin L, endothelial sialidases, and heparanase through TLR-4, similar to bacterial infection via LPS." (PMID 36671689, 2023). "TLR4 is believed to be part of the first immune barrier to bacterial infection in the gastrointestinal tract and can promote the release of cytokines by activating the NF-κB signaling pathway, thus activating innate immune response." (PMID 37107392, 2023). "GO analysis showed that “protein localization to endoplasmic reticulum” pathway decreased during this cell model; and endoplasmic reticulum (ER)-localized Hrd1 expanded TLR4 signal induced inflammation during bacterial infection." (PMID 36844408, 2023). "It was also seen hepatocytes can recognize LPS by TLR4 and activate to protect the liver from bacterial infection." (PMID 37153436, 2023). "All of these immune responses (interferons, cytokines, and chemokines) are also activated during bacterial infections via lipopolysaccharide (LPS) through toll-like receptor 4 (TLR4) signaling." (PMID 37361874, 2023). "LPS are widely used in experimental models of systemic bacterial infection and trigger robust inflammation by potently activating TLR4 expressed on innate immune cells." (PMID 38001534, 2023). "The nociceptor expression of TLR4 highlights its role in the host immune response to bacterial infections." (PMID 37627258, 2023). "It has been shown that TLR4 signaling in macrophages can activate hundreds of genes that contribute to the protection against bacterial infection." (PMID 37106866, 2023). "Typical host response to bacterial infection is mediated via TLR4/lipopolysaccharide signaling that triggers pro-inflammatory reactions." (PMID 37174635, 2023). "In endothelial cells (ECs), stimulation of Toll-like receptor 4 (TLR4) by the endotoxin lipopolysaccharide (LPS) induces the release of diverse pro-inflammatory mediators, beneficial in controlling bacterial infections." (PMID 36899833, 2023). "Previous studies have documented TLRs, particularly TLR2 and TLR4 play a crucial role in regulating the intensity of the immune-inflammatory response during bacterial infection." (PMID 35413908, 2022). "In the context of bacterial diseases, miR-17-5p has been shown to down-regulate lipopolysaccharide (LPS)-induced Toll-like-receptor 4 (TLR4)-mediated inflammation, thus favoring a balanced immune response." (PMID 35857780, 2022).
bacterial infection (continued). "The pathways which induce calprotectin expression and secretion during bacterial infection start with bacterial lipopolysaccharides (LPS) binding to a toll-like receptor 4 (TLR4) on phagocytes." (PMID 35359908, 2022). "Toll-like receptor 4 (TLR4), which is present on the surface of platelets and activated by lipopolysaccharides (LPS) secreted during bacterial infection, encourages binding to neutrophils and promotes NETosis events in pulmonary capillaries." (PMID 35634307, 2022). "Among the antigen-presenting cell cluster, Toll-like receptor (TLR) expression patterns suggested a response tuned more toward bacterial infection (higher TLR4 and TLR5 expression)." (PMID 35962188, 2022). "Much of the previous work implicating TLR4 in MDD have primarily focused on the role of TLR4 following activation by LPS in bacterial infections." (PMID 35782423, 2022). "As well-known inflammatory cytokines or chemokines, IL-1β, IL-8, IL-6, TNF-α and TLR4 are involved in various types of inflammatory responses, and play key roles in the inflammatory process during bacterial infection of bovine mammary glands." (PMID 36233122, 2022). "Generally, TLR4 plays a key role in intestinal pattern recognition (recognizing bacteria lipopolysaccharides) during bacterial infection in mammals." (PMID 36177013, 2022). "The effect of miRNAs in the regulation of cytokines and bacterial infection were investigated, especially in the regulation of miR-194a-5p on the TLR4 pathway." (PMID 35598011, 2022). "Two years later, Beutler built on this observation by describing a Toll-like gene, tlr4, as the receptor for the bacterial product LPS, representing a crucial step in innate immune activation and protection from bacterial infections in mammals." (PMID 36231089, 2022). "TIRAP, also known as MYD88 adapter-like (Mal), is an important link between MYD88 and the receptor complex formed by TLR2 and TLR4 activation following bacterial infection." (PMID 35140801, 2022). "TLR4, a key receptor of innate immunity, is a critical driver of immune responses to bacterial infections and a critical link in various aberrant inflammatory responses." (PMID 36523959, 2022). "In mammals, human MD2 binds LPS and TLR4 to form a ternary complex, and the TLR4 signaling pathway is activated to produce proinflammatory factors against bacterial infection." (PMID 36643915, 2022). "This allows TLR4 to act as a sensor for bacterial infection and transduce a signal to activate the inflammatory response through NF-κB." (PMID 33554122, 2021). "Here the authors implicate mechanical sensor Piezo1 in the TLR4 mediated host response to bacterial infection and implicate it in the enhancement of macrophage mediated host response." (PMID 34112781, 2021). "The TLR4 signaling pathway is an immune pathway that allows cells to respond to bacterial infections by sensing LPS on bacterial cell walls." (PMID 33554122, 2021). "Therefore, again, the human data correlate with the mouse model; collectively, the data suggest that downregulation of TLR2 and/or TLR4 as a result of heme released by traumatic injuries may be an important cause of increased clinical susceptibility to bacterial infection." (PMID 34520397, 2021). "Placental TLR3 and TLR4 have been previously reported to induce premature termination of pregnancy upon detection of viral and bacterial infection, respectively." (PMID 34395439, 2021). "Gal-3 was shown to act as a natural paracrine ligand for the Toll-like receptor 4 (TLR4) and to thereby be responsible for inflammation in the lipopolysaccharide (LPS) model of bacterial infection." (PMID 34831271, 2021). "The results showed that the overexpression of TLR4 during the initial stages of bacterial infection (10 and 30 min) led to more monocytes undergoing internalization, and the fluorescence signals from these cells were more intense." (PMID 33966642, 2021).
bacterial infection (continued). "Above all, TLR4, as a mammalian receptor for LPS, is vitally beneficial to the control of bacterial infections." (PMID 33714207, 2021). "C3H/HeJ mice carry a missense mutation in the third exon of the TLR4 gene causing their hyporesponsiveness to LPS, and they have been widely used to examine the role of TLR4 signaling against bacterial infections." (PMID 33763386, 2021). "TLR4 expression on cell surface of innate immune cells plays an indispensable role in regulating the progression of host reaction and inflammation in bacterial infection by activating signal transduction pathways." (PMID 34282120, 2021). "TLRs are involved in the recognition of and response to bacterial infections, and TLR4 in particular is activated through binding to lipopolysaccharide (LPS)." (PMID 33806791, 2021). "The bacterial infection presumably triggers the release of CGRP via activation of TLR4, thus in any event it is a bidirectional phenomenon." (PMID 33318075, 2021). "One mechanism reported for certain BRMs, for example, is to act like TLR agonists, particularly TLR-2 and TLR-4 in bacterial infections, helping enhance the response to microbial infections." (PMID 34696778, 2021). "IFN production is induced in macrophages downstream of endosomal TLR4 signaling during both bacterial infection and purified LPS stimulation." (PMID 33684179, 2021). "In particular, ME-CSCs exhibited a pronounced inflammatory footprint characterized by a significantly increased expression of the TLR4, a receptor recognizing bacterial LPS in the first line defense against bacterial infections." (PMID 31947538, 2020). "Similar effect was also observed in a bacterial infection model in which in vivo LPS application induces proliferation of dormant HSCs via TLR4 and sustained LPS exposure impairs HSC self-renewal and competitive repopulation activity." (PMID 32373117, 2020). "It is well-known that TLR4/MYD88 is responsible for the upregulation of NF-κB signaling in response to bacterial infection in various conditions." (PMID 32110933, 2020). "The transmembrane glycoprotein TREM1, which is found in monocytes, macrophages and neutrophils, is also heavily involved in TLR4 signaling, i.e., it promotes inflammation in response to bacterial infection." (PMID 32325790, 2020). "TLR4 also can be activated by LPD derived from bacterial co-infection or secondary bacterial infections, which have been found in up to 14% of SARS-CoV-2 infected patients." (PMID 33362782, 2020). "To validate the role of TLR4 in macrophages response to bacterial infection, we blocked TLR4 with TLR4-IN-C34, a TLR4 antagonist." (PMID 33212859, 2020). "LPS is a potent agent that activates the innate immune response via the TLR4 pathway, and its use provides information about the effects of host inflammatory response, which occurs in bacterial infections." (PMID 32546185, 2020). "This is the first report to show that TLR4 on the bladder urothelium couples neural signaling to the defense against bacterial infection, resulting in urinary frequency." (PMID 33273625, 2020). "In order to determine the effect of bacterial infection on TLR2/TLR4 expressions on macrophages, we infected PMA-activated THP-1 with MAP for 24 h." (PMID 33212859, 2020). "Signaling via Toll-like receptor 4 (TLR4) in macrophages constitutes an essential part of the innate immune response to bacterial infections." (PMID 30872589, 2019). "In macrophages, TLR4 activation reduces LXRs activation and decreases LXRs target gene expression after bacterial infection, suggesting a crosstalk between the two signaling pathways." (PMID 31708874, 2019). "Overall, this study showed that PBD-2 protected against bacterial infection through a direct bactericidal activity and alleviated inflammation by interfering with the TLR4/NF-κB pathway." (PMID 31379864, 2019). "And there are a number of in vivo animal studies that demonstrated bacterial infection related to preterm delivery through TLR4 signaling." (PMID 31507429, 2019).
bacterial infection (continued). "In the present study, LPS treatment, which models bacterial infection via TLR-4 activation, decreased ABCG2 mRNA and BCRP protein expression in HTR-8/SVneo cells." (PMID 31561453, 2019). "Other studies have demonstrated that LL37 inhibits inflammation by neutralizing LPS and inhibiting TLR4 activation in bacterial infections." (PMID 30842778, 2019). "On the other hand, it is known that the activation of the TLR4 pathway is not only driven by the presence of lipopolysaccharide (LPS) from bacterial infections but also by endogenous activators as HSP60 and HSP70." (PMID 29774096, 2018). "As miR-146a is a negative regulator of TLR4 and increased expression of this miRNA results in a decrease in TLR4 responsiveness in neonatal monocytes, this prevents a robust pro-inflammatory response to bacterial infection." (PMID 29515570, 2018). "It is known that the activation of the TLR4 pathway is not only driven by the presence of lipopolysaccharides (LPS) from bacterial infections but also by endogenous activators." (PMID 29774096, 2018). "On the other hand, TLR4 has been widely demonstrated to be involved in the identification of pathogens, thereby implicating TLR4 as an innate immune sensor for bacterial infection and tissue injury." (PMID 30186181, 2018). "The localization of Lcn2-R in the inner medulla is intriguing considering local bacterial infections trigger toll-like receptor-4 (TLR-4)-mediated secretion of the bacteriostatic Fe3+-free (apo-)Lcn2." (PMID 30404645, 2018). "Chronic TLR4 activation in bacterial infection with persistent lipopolysaccharide produces anti-inflammatory IL10, and in Aspergillus sp." (PMID 28573109, 2017). "CD14 binding to toll-like receptor 4 (TLR4) lead to activation of pro-inflammatory signalling cascade in bacterial infection." (PMID 28794881, 2017). "TLR4, one of the important PRRs, plays a critical role in the innate immune response against bacterial infections." (PMID 29050341, 2017). "The induction of type I interferon in macrophages and dendritic cells in response to bacterial infections has been canonically traced to MyD88-independent signaling via TLR4 responses to LPS." (PMID 28453531, 2017). "Recent studies have shown that, binding of TLR4 to endogenous or exogenous ligands (from viral or bacterial infection) activates downstream NF‐κB signalling, which enables microglial activation and induces the release of pro‐inflammatory cytokines." (PMID 28842949, 2017). "As well, considering that LPS is the main ligand of TLR-4, SNP within TLR-4 gene has been reported to increase the susceptibility to bacterial infections." (PMID 28210435, 2017). "In conclusion, GrA and GrK13 use differential mechanisms to enhance TLR4 signaling during bacterial infections." (PMID 28028441, 2016). "Toll-like receptor 4 (TLR4) activation by bacterial infection, or by sterile inflammatory insult is a primary trigger of spontaneous preterm birth." (PMID 27819333, 2016). "We have investigated mechanisms of PKR activation in response to a common intracellular bacterial infection; Chlamydia trachomatis, and the role that TLR4, ER stress and the NADPH oxidase system play in the process." (PMID 27021640, 2016). "Polymorphisms in TLR4 and MICA are examples of these changes and have been related to the biology of the inflammatory responses to bacterial infections." (PMID 27559544, 2016). "We observed that genes indicative of bacterial infection and inducers of inflammation, namely Tlr4 and RegIIIγ were expressed at lower amounts in mice consuming the WB-enriched diet compared to RS-enriched diet." (PMID 28031748, 2016). "Toll-like receptor 4 (TLR4) is an inflammatory receptor expressed at high levels on macrophages, which is activated in response to bacterial infection and/or sterile tissue damage." (PMID 27077881, 2016).
bacterial infection (continued). "Induction of iNOS upon bacterial infection of macrophages is a host response reported to enhance antimicrobial activity through activation of the TLR4 pathway as well as IFN signaling." (PMID 26284031, 2015). "In previous studies, mouse macrophages were primed with LPS, which strongly induces TLR4-mediated NF-κB activation, prior to bacterial infection; this would mask NLRP3-mediated NF-κB activation." (PMID 25761061, 2015). "Here we have found that AnxA2 expression is a key step in negative regulation of inflammatory responses to bacterial infections, acting as a molecule to induce internalization of TLR4, followed by recruitment to early endosomal membranes." (PMID 26527544, 2015). "LPS injection is a common way to activate immune response, as LPS is recognised by toll-like receptor 4 (TLR4) on antigen-presenting cells and effectively models bacterial infection." (PMID 24891958, 2014). "Bacterial infections activate innate immune signaling pathways involving toll-like receptor 4 (TLR4) and the transcription factor NF-κB in microglia and macrophages, which induces the expression of pro-inflammatory cytokines and the production of nitric oxide." (PMID 24886300, 2014). "80% of the monocytes expressed TLR4 and thus were responsive to danger signals from bacterial infection derived LPS as well as from endogenously derived stress signals like HMGB1 and hsp." (PMID 25254631, 2014). "During bacterial infection, LPS extracted from the bacterial membrane is transferred to TLR4 by two accessory proteins, LPS-binding protein and CD14." (PMID 24465739, 2014). "The binding of TLR4 to LPS in a bacterial infection results in the macrophages/monocytes becoming activated allowing them to produce pro-inflammatory cytokines, which assist in clearing the infections." (PMID 23984304, 2013). "TLR4 is important in protecting the body from bacterial infections through binding lipopolysaccharides (LPS) found on the surface of Gram-negative bacteria such as E. coli." (PMID 23984304, 2013). "TLR4 is important in mediating inflammatory cytokine production in response to bacterial infection, and LPS is the main ligand binding to TLR4 to induce inflammation." (PMID 24155891, 2013). "TLR4 is a host cell membrane receptor that detects lipopolysaccharide from Gram-negative bacteria and elicits innate immune response following bacterial infection." (PMID 23758641, 2013). "These TLR4-induced MDSCs accumulate with delayed kinetics after high dose LPS exposure or bacterial infection and have features of PMN-MDSCs." (PMID 24066282, 2013). "LPS binds to and triggers TLR4 signalling in innate immune cells, and only mimics certain aspects of a bacterial infection." (PMID 22738332, 2012). "TLR4 plays a central role in the signaling pathways that control the innate immune response in response to viral or bacterial infection." (PMID 21559380, 2011). "Several studies have highlighted a role for TLR4 in bacterial clearance; for example activation of TLR4 by Klebsiella pneumoniae has been shown to be critical for induction of IL-17, known to be important in host defence against bacterial infection." (PMID 21738466, 2011). "CDCs respond to bacterial infections and mediate the associated exacerbations in SLE patients, and they have been found to release IFN-alpha upon TLR4 ligation following priming with IFN-beta, consistent with their apparent involvement here." (PMID 19568420, 2009). "This indicates that the response to bacterial infection is not only dependent on LPS signaling via TLR4 but signaling through other Toll-like receptors also plays an important role." (PMID 18612392, 2008). "For example, some subjects with TD have lower expression of the toll-like receptor 4 (TLR4) after stimulation with lipopolysaccharide (mimicking a bacterial infection), and higher levels of soluble Cluster of Differentiation (CD) 14, compared to healthy subjects." (PMID 40869088, 2025).